ELN (elastin)
Diseases named in the same sentence as ELN in open-access papers (continued):
Sharing a sentence is not in itself a finding about the gene and the disease.
aneurysm (continued). "Its inhibition was previously reported to increase the stability of atherosclerotic plaques and aneurysm by promoting the production of elastin and collagen." (PMID 35329950, 2022). "These Fbn1mgR/mgR mice develop aneurysms similarly to human Marfan patients, showing vascular inflammation and elastin degradation in the aortic wall, and die at around 4 months as a result of aortic dissection." (PMID 35492343, 2022). "The proteins identified in the aneurysm wall include the structural fibulin-5 involved in elastin assembly, the anti-aggregatory and vasodilatory PGI2-producing enzyme prostacyclin synthase, and the water channel aquaporin-1 (AQP1)." (PMID 35203568, 2022). "At the biomechanical level, elastin is responsible for the passive recoil of vascular tissue during pulsatile loading, and elastin fiber degradation is a key feature of aneurysm dilation." (PMID 33925413, 2021). "After induction of aneurysm by 4-week infusion of angiotensin II (Ang II), two biweekly intravenous injections of pentagalloyl glucose (PGG)-loaded nanoparticles conjugated with elastin antibody delivered the drug to the aneurysm site." (PMID 33883612, 2021). "Taken together, this mutational repertoire strongly suggests that interference with the assembly and function of elastic lamellae, and therefore impairment of the elastin-contractile unit, is an initiating event in aneurysm pathogenesis." (PMID 33514025, 2021). "It was also found that elastin rupture in the tunica media was significantly smaller in KO mice than in the control group 10 weeks after aneurysm induction." (PMID 34456984, 2021). "The medial fraction of elastin was decreased in aneurysms, whereas that of cytoplasm, collagen, and glycosaminoglycans were similar." (PMID 34162971, 2021). "H&E and VVG staining of suprarenal aortic sections from all three groups of aneurysms harvested at week four right after the Ang II infusion provided information about the morphology, cellular infiltration, and elastin degradation of the tissues." (PMID 33883612, 2021). "Our VVG staining results indicate the replenishment of elastin fibers that are lost during aneurysm development in the PGG-NP treated group." (PMID 33883612, 2021). "Although effective non-surgical options for aneurysm repair have yet to be developed, our group has investigated cell-based therapies to restore elastin in murine models of elastase induced aneurysm." (PMID 33925413, 2021). "In aneurysms featured by elastin breakdown, structural products of EDPs and desmosine in plasma increased and correlated with aneurysm rupture and aneurysm-related death." (PMID 33993833, 2021). "Tβ4-null mice displayed aortic VSMC and elastin defects that phenocopy those of LRP1 mutants, and their compromised vascular integrity predisposed them to Angiotensin II–induced aneurysm formation." (PMID 33784254, 2021). "Previous studies examining the effect of vitamin D deficiency on elastic elements showed that abdominal aortic aneurysms have significantly lower levels of elastin in the intima-media composites of male aneurysm walls than of females." (PMID 34360792, 2021). "We previously demonstrated that administering 100,000 ASCs periadventitially to a murine aneurysm model can preserve elastin fiber integrity." (PMID 33925413, 2021). "Human aneurysms frequently exhibit a decreased elastin/collagen ratio, owing to preferential degradation of elastin coupled, in some instances, with increased collagen deposition." (PMID 34617062, 2021). "During the third trimester, as detected by ultrasound, dilatation and aneurysm development has been ascribed to the weakening of the parietal wall with a reduction of intimal cushion formation or deposition of elastin." (PMID 34436233, 2021). "An increased proteolytic activity on collagen and elastin in the context of aneurysm walls has been described in previous studies." (PMID 33573220, 2021).
aneurysm (continued). "Doxycycline is a kind of tetracycline antibiotic which is capable to suppress a cast of MMPs, and has been shown to be effective in reducing elastin degradation and aneurysm development in murine AAA models." (PMID 33613530, 2020). "It is important to point out that we started our therapy on day 14 after elastase treatment where substantial elastin fragmentation and aneurysm development was already taken place." (PMID 32218565, 2020). "MMP12 is recognized as degrading soluble and insoluble elastin; inducing pro-osteogenic calcification in aortic valve disease; and playing a role in aneurysm formation, lung dysfunction, and chronic obstructive pulmonary disease." (PMID 32098116, 2020). "Physiologically, an aneurysm wall has decreased elastin and increased collagen in its structure, due to the degradation of elastin, mainly by MMP-2 and MMP-9." (PMID 33419373, 2020). "In another study, DPP4 inhibition decreased the formation of aneurysm, elastin degradation, expression of MMP2 and -9, gelatinolytic activity, aortic apoptotic signal and macrophage infiltration in a mouse model, with similar results shown for GLP-1." (PMID 31971988, 2020). "Elevated levels of MMP-9 and MMP-2 are responsible for the formation and size of aneurysms, as they contribute to the degradation of elastin." (PMID 33419373, 2020). "After the use of NT-2300, which is a cysteine protease inhibitor, it was observed that cathepsin activity and collagenase 1 and 4 activity in the aneurysm wall decreased while the level of elastin increased." (PMID 33224650, 2020). "Together, these data suggest that the treatment with DAPT results in partial restoration of elastin and collagen fibers, thereby resulting in aneurysm stability." (PMID 31530833, 2019). "Correlating with reduced aneurysm size, apocynin significantly reduced elastin breakdown in Fbn1C1039G/+ mice (1.72 ± 0.71 breaks/lamina, n = 10, P = .002)." (PMID 31402541, 2019). "In the presence of aneurysms, both tissues show significant thickening of the wall and in particular in aortic aneurysms the collagen content is significantly increased, while elastin is substantially reduced." (PMID 30867924, 2019). "Immunodetection of glucose transporter 1 (GLUT1), a marker of chronic tissue hypoxia, was minimal in non-aneurysmal medial specimens, and locally accumulated within regions of elastin degeneration, particularly in TAV-associated aneurysms." (PMID 30276199, 2018). "The similarities of certain miRNA expression profiles in both TAA and AAA suggests a role for them in the common pathways of aneurysm progression such as degeneration of the collagen and elastin matrix and defective SMC function in the aortic wall." (PMID 28425970, 2017). "We determined that miR-181b negatively regulates macrophage tissue inhibitor of metalloproteinase-3 expression and vascular smooth muscle cell elastin production, both important factors in maintaining atherosclerotic plaque and aneurysm stability." (PMID 27756793, 2017). "It has been reported that MMPs synthesis and activity are increased in rat and human aneurysm tissue, especially MMP2 and MMP9, which can degrade elastin, resulting in less flexibility and loss of the integrity of the vessel walls." (PMID 28164126, 2017). "miR‐29b inhibition resulted in aneurysm reduction, increased elastogenesis, decreased matrix metalloproteinase activity and decreased elastin breakdown." (PMID 28455451, 2017). "Our results revealed in principle that inhibition of RIP1 slows aneurysm progression by reversing SMC loss, disrupting vascular inflammation and promoting synthesis of elastin." (PMID 28186202, 2017). "The elastin and fibrillin content was reduced in aortic media from aneurysms in both BAV and TAV patients." (PMID 26904289, 2016). "Treatment with anti-inflammatory agents or MMPs antagonists can lead to preservation of elastin in the media and reduction in experimental aneurysm development." (PMID 26918963, 2016).
aneurysm (continued). "TNF-α mediates inflammatory response and incites MMPs release, down-regulate elastin gene expression and initiates aneurysms." (PMID 26918963, 2016). "Histologically, the aneurysms are characterized by the near total destruction of the elastin matrix of the media." (PMID 27965979, 2016). "The aneurysm walls differed in the distribution of elastin, the presence of fibrosis, and the thickness of the vessel layers." (PMID 25608574, 2015). "Because excessive elastolysis mediated by MMP-9 is considered a critical step in aneurysm development, we determined the degree of medial elastin disruption in the CaCl2+PBS and CaCl2+decorin groups." (PMID 25781946, 2015). "To further characterize vessel wall remodeling in aneurysms, we analyzed elastin integrity by Verhoeff-Van Gieson (VVG) staining." (PMID 25985281, 2015). "Histopathological examination revealed disruption of medial elastin, an increase in collagen content and smooth muscle cells, and neointima formation in aneurysm grafts." (PMID 25068788, 2014). "Several recent studies describe the involvement of miR-29 in aneurysm formation by post-transcriptionally repressing the expression of extracellular matrix proteins such as collagens, elastin, and fibrillins." (PMID 24079748, 2013). "Additionally, enzymes such as MMP-12 primarily degrade elastin, weakening the arterial walls and promoting aneurysm formation." (PMID 40643529, 2025). "For instance, Boersen et al29 mentioned that their thin-walled phantoms may be more elastic in comparison with in vivo condition, since aneurysms are usually stiffer because of a larger volume of collagen and less volume of elastin and muscle cells." (PMID 38149463, 2025). "Patients with aneurysms are known to have potential defects in collagen and elastin production, suggesting that connective tissue abnormalities may affect wound healing, predisposing patients to incisional hernia following abdominal aortic aneurysm repair." (PMID 41488881, 2025). "We hypothesize that the higher serum desmosine levels observed in patients who experienced subarachnoid hemorrhage, compared to the control group, can be attributed to the breakdown of elastin released from the damaged aneurysm tissue during the rupture." (PMID 40142864, 2025). "Similar to atherosclerosis, aneurysm pathology is complex, involving immune cell infiltration, inflammation, oxidative stress, protease-mediated collagen and elastin degradation and VSMC apoptosis.These processes result in restructuring of the vascular wall and dilation." (PMID 41226315, 2025). "This approach could potentially be translated to intracranial aneurysms, where elastin degradation plays a central role in aneurysm expansion." (PMID 39595942, 2024). "A decrease in elastin content, disrupting the collagen-to-elastin ratio balance, may influence the pathogenesis of various types of aneurysm and other aortic diseases, including atherosclerosis." (PMID 38334666, 2024). "Hence, overexpression of TIMP-1 in a rat model of guinea-pig xenograft-induced AAA reduced elastin degradation together with aneurysm formation and rupture." (PMID 37799778, 2023). "In the early stages of aneurysm, the basement membrane components that contain collagen increased in the thickened area, and the basement membrane becomes thin from the degeneration of elastin and depletion of smooth muscle cells in the later stages." (PMID 37378402, 2023). "Moreover, vascular injury has been associated with a high ETS1 expression, and the simultaneous inhibition of ETS1 and NF-κB in a rabbit model of AAA preserves elastin integrity and reduces aneurysm size." (PMID 37698712, 2023). "In this study, we hypothesize that CAG inhibits the progressive dilatation of AAA in the rat PPE aneurysm-model by its anti-inflammatory and anti-oxidative effects leading to reduced protease activity and, thereby, preserving elastin integrity." (PMID 35203568, 2022).
aneurysm (continued). "In addition, matrix metalloproteinase 9 (MMP9) is activated by TNF-α, which leads to the destruction of elastin and aneurysms formation in the blood vessel wall, and increased NO concentration, which leads to the blood vessel wall's expansion and damage." (PMID 35924269, 2022). "We especially modelled aneurysm progression following localized elastin degradation in the ATA." (PMID 35067825, 2022). "Previous reports revealed that both IL-10 and TGF-β could promote VSMC proliferation and elastin expression, thus counteracting aneurysm progression." (PMID 35228523, 2022). "They showed that ADAMTS-4 deficiency resulted in reduced aneurysm and dissection formation, with associated maintenance of normal elastin fibre arrangements, reduced inflammatory cell infiltration and apoptosis, with reduced versican degradation." (PMID 36012466, 2022). "In pathway analysis with correlated genes with these two candidate genes (FRZB and C1orf24), we showed the pathways were related to VSMC and elastin fiber formation, which might imply these candidate genes are involved in aneurysm integrity." (PMID 33245093, 2021). "TNF-α induced elastin degradation is associated with vasculitis caused by Kawasaki disease and vascular aneurysms, and the TNF-α deficiency prevents elastin degradation and aneurysm formation." (PMID 34917605, 2021). "We not only show that such targeted delivery regresses aneurysms, but we also show that such therapy restores elastin lamina, decreases matrix metalloproteinase (MMPs), immunomodulating cytokine TGFβ1, and infiltration of activated macrophages at the aneurysmal site." (PMID 32218565, 2020). "The purpose of this study is to test if our novel targeted NP based PGG delivery that only targets degraded elastin could reverse already developed aneurysms in elastase-induced AAA." (PMID 32218565, 2020). "While these changes suggest a largely protective role for Notch3 with regards to aneurysm biology, Notch3 may act as an inhibitor of ELN expression in vitro." (PMID 31886938, 2020). "Nec-1s treatment from 7 to 14 days after aneurysm induction not only significantly slowed aneurysm growth, but also preserved the histological structure of the aorta (decreased elastin disruption and preserved SMC layer), but also decreased inflammatory cell infiltration into the vessel wall." (PMID 33142926, 2020). "Isenberg and colleagues applied PGG periadventitially to the abdominal aorta of adult male Sprague–Dawley rats, previously exposed to CaCl2-mediated aortic elastin injury, and found that early inhibition of aneurysm and stabilization of elastin lamellae is possible." (PMID 31277241, 2019). "Combining scanning X-ray microdiffraction and small-angle scattering reveals the crystalline phases of microcalcifications, and the abundance and orientation of collocated fibrous tissues (elastin, collagen, myofilament), spatially resolved over aneurysm tissue samples." (PMID 30867924, 2019). "This may contribute to the thinner lamellae and elastin fragmentation observed in mgR mice prior to aneurysm formation." (PMID 29040313, 2017). "Moreover, miR-181b inhibition greatly increased elastin and collagen expression, promoting a fibrotic response and subsequent stabilization of existing plaques and aneurysms." (PMID 27756793, 2017). "It has also been demonstrated that inflammation may play an important role in aneurysm progression, through the elastin breakdown and SMCs apoptosis mediated by inflammatory cells infiltration and activation of matrix metalloproteinases (MMPs)." (PMID 25243605, 2014). "As previously suggested, this could work through neutrophils secreting proteolytic enzymes in response to cigarette smoke, promoting degradation of elastin and collagen and thus formation of aneurysms." (PMID 24708536, 2014).
aneurysm (continued). "Given that SMC dysfunction and elastin degradation are central to the progression of both aortic and intracranial aneurysms, hyaluronic acid nanoparticles could be adapted to stimulate elastin production in cerebral arteries, potentially slowing aneurysm growth." (PMID 39595942, 2024). "Given the genetic predisposition for elastin degradation in Marfan patients and the accompanying remodeling of the ECM, gaining insight on the degradation, synthesis, and structure of vascular collagen fibers is crucial for understanding the underlying mechanisms of aneurysm progression." (PMID 39795873, 2024). "Assessment of spontaneous AAA formation in long-term high fat-fed Apoe−/− mice with and without Mmp3-deficiency revealed increased presence of aneurysms in Mmp3 wild-type mice, as characterised by elastin fragmentation, aortic wall thinning, and rupture of medial elastin fibres." (PMID 37799778, 2023). "Also, the STAT3 inhibitor, BP-1-102, can reduce the expression of inflammatory factors and MMPs bound to NF-kB by inhibiting the activation of the JAK/STAT3/NF-kB pathway, and then restore the vascular wall elastin to reduce blood pressure, thereby treating aneurysms in mice." (PMID 38137108, 2023). "Additionally, in humans, elastin insufficiency is associated with inherited obstructive arterial disease but not aneurysm." (PMID 35463747, 2022). "While degeneration of elastin fibers due to aneurysm growth is also responsible for weakening of the aortic wall, understanding the biomechanics of the thoracic aortic aneurysms (TAAs) and hemodynamics of the blood may significantly contribute to clinical diagnosis and treatment." (PMID 36143333, 2022). "Although the limited lifespan of elastin-deficient mice prevents their long-term observation, complete loss of elastic lamellae—and thus of the elastin-contractile unit—does not appear to be sufficient to initiate the development of aneurysm." (PMID 33514025, 2021). "They found that the aneurysm tissues were less extensible than the healthy counterparts, and that most of the changes in the tension-stretch curves between the two tissue groups were in the low-stress region, suggesting possible alterations in the elastin component of the tissue." (PMID 33568740, 2021). "MMP9 could destroy elastin and play a role in outward remodeling and aneurysm formation." (PMID 32911750, 2020). "However, the elastin content of real aneurysms is inferior to that of healthy arteries." (PMID 32230757, 2020). "Notably, new elastin production by adult cells has been something of a holy grail in the field of vascular regenerative medicine, with several recent studies in the field of aneurysm therapeutics focused on production of this important molecule." (PMID 31214600, 2019). "Furthermore, differences in collagen and elastin interference factors, as well as hormonal changes, may contribute to aneurysm formation." (PMID 31836842, 2019). "Structural, biochemical and also genetic studies have shown that elastin degradation plays an important role in aneurysm formation, and aneurysms can be induced by experimental injection of porcine pancreatic elastase, although this may relate to other components than the elastase itself." (PMID 29470511, 2018). "Additionally, absence or aberrations in elastin content are felt to contribute to both aneurysm formation and eventual weakness leading to rupture, and its thickness in certain areas of the circulation may play a role in the risk of rupture predicted by previous studies." (PMID 40566064, 2025). "Another reason why our results need to be reproduced in patients with UIAs is that in unruptured aneurysms, elastin degradation is likely a much slower process, whereas in ruptured cases, the acute vascular wall disruption may lead to a significantly greater release of elastin degradation products." (PMID 40142864, 2025).